IGKV2-19 (immunoglobulin kappa variable 2-19 (pseudogene))
Synonyms: A28; IGKV219
Gene: Immunoglobulin variable (V) pseudogene on chromosome 2 (89,134,975 to 89,135,257, reverse strand). Ensembl gene ENSG00000253732.
Diseases named in the same sentence as IGKV2-19 in open-access papers:
IGKV2-19 is named in the same sentence as 1 disease in open-access papers, as found by Europe PMC text mining. Sharing a sentence is not in itself a finding about the gene and the disease.
IGKV2-19 shares sentences with these, for which no sentence is quoted: viral infection (1 paper).